MMP12 (matrix metallopeptidase 12)
Diseases named in the same sentence as MMP12 in open-access papers (continued):
Sharing a sentence is not in itself a finding about the gene and the disease.
colon carcinoma (15 papers, 2016 to 2024). "As we have observed for MMP7 and MMP10, we found that elevated abundance of serum MMP12 in colon cancer patients is associated with a significantly shortened overall survival." (PMID 27431388, 2016). "It has been shown that MMP12 is highly expressed in colon cancer patients and predicts a poor prognosis, which is consistent with the results of our qPCR." (PMID 36544770, 2022). "Both MMP9 and MMP12 proteins were increased in colon cancer epithelial cells compared to controls, with MMP12 proteins having more than 2-fold increase, while MMP9 proteins had a 1.3-fold increase in cancer cells compared to normal cells." (PMID 32171282, 2020). "Cancer-by-cancer, lung squamous (LUSC) has two MMPs with sensitivities over 95% (MMP11 and MMP12), colon cancer (COAD) has three over 94% (MMP11, MMP28, and MMP7), and esophageal cancer (ESCA) has two over 94% (MMP11 and MMP12)." (PMID 31200666, 2019). "Overexpression of MMP12 was observed in various cancers, including gastric cancer, colon cancer and hepatocellular carcinoma." (PMID 30305064, 2018). "To our knowledge we are the first to demonstrate the influence of serum MMP10 and MMP12 on colon cancer patients ́ survival." (PMID 27431388, 2016). "Luminex based expression analysis revealed a significant overexpression of MMP7 and an overexpression of MMP10 and MMP12 in the sera of colon cancer patients compared to the healthy control group." (PMID 27431388, 2016). "In the present study we investigated the expression of MMP7, MMP10 and MMP12 in serum specimens in a homogenous collective of colon cancer patients with regard to clinicopathological characteristics and patients ́ prognosis." (PMID 27431388, 2016). "Taken together our results propose that MMP7, MMP10 and MMP12 are increased in sera of colon cancer patients when compared to healthy donors and MMP12 seems to play a role in vascular invasion." (PMID 27431388, 2016). "The present investigation yielded MMP7, MMP10 and MMP12 serum levels in a homogenous group of colon cancer patients to be adverse prognostic molecular markers exerting valid multiplex bead-based immunoassay - technologies." (PMID 27431388, 2016). "In summary, our results imply a significant influence of serum MMP7, MMP10 and MMP12 in human colon cancer dissemination with considerable impact on overall survival." (PMID 27431388, 2016). "The expression of MMP7, MMP10 and MMP12 were determined in serum samples of 78 colon cancer patients and 38 serum samples of healthy individuals using Luminex 100TM technology." (PMID 27431388, 2016). "Expression patterns of MMP7, MMP10 and MMP12 in colon cancer patients ́ sera are different compared to serum specimens of healthy individuals." (PMID 27431388, 2016). "After having confirmed differences in the expression of MMP7, MMP10 and MMP12 concentrations in colon cancer patients ́ serum samples and serum samples of a healthy control group we correlated these results with patients’ overall survival." (PMID 27431388, 2016). "We suggest a tumor promoting role of MMP12 due to impaired overall survival in colon cancer patients expressing higher serum level of MMP12." (PMID 27431388, 2016). "MMP12 was found to be correlated with a dismal prognosis in colon cancer patients’ serum." (PMID 36532065, 2022). "Thus, in advanced colon cancer (CRC), high levels of MMP-12 have been associated with better prognosis, while increased levels of TIMP, the negative tissue regulator of MMP, correlated with a negative prognosis in that cancer." (PMID 33126765, 2020). "Serotonin is essential for the growth of s.c. colon cancer allografts in vivo by acting as a regulator of angiogenesis which reduces the expression of matrix metalloproteinase 12 (MMP-12)—an endogenous inhibitor of angiogenesis—in tumor-infiltrating macrophages." (PMID 30576312, 2018). "Moreover overexpression of MMP7, MMP10 and MMP12 in colon cancer patients ́ sera displayed a significantly impaired overall survival." (PMID 27431388, 2016).
colon carcinoma (continued). "However divergent evidence exists that - opposing to MMP7 and MMP10 - MMP12 diminishes colon cancer growth in vitro and has a favorable impact on overall survival in colorectal cancer patients." (PMID 27431388, 2016). "Similarly, we observed a higher abundance of MMP10 (p = 0.128) and MMP12 (p = 0.544) in colon cancer patients` sera as compared to serum specimens of healthy individuals." (PMID 27431388, 2016). "Furthermore, overexpression of MMP7, MMP10 and MMP12 in colon cancer patients ́ sera correlates with a dismal prognosis and may help to stratify patients into different risk groups." (PMID 27431388, 2016). "To investigate the effect of inhibiting MMP12 on colorectal cancer or body weight, we administered MMP12 inhibitor (MMP408) and its combination with a classic clinical anti-colon cancer drug (5-FU) in ApcMin/+ mice." (PMID 34863141, 2021). "Given abnormal levels of MMP9, MMP12 and TIMP3 mRNA expression in tumors from CRC patients and controls, we next measured the level of the MMPs and TIMP3 proteins in human colon cancer epithelial cells compared to normal colon cells by immunoblot." (PMID 32171282, 2020). "This controversial finding also is seen in other tumors; for instance, patients with hepatocellular or colon carcinomas whose tumors express MMP12 mRNA have better survival than those whose tumors do not express MMP12 and thus do not produce angiostatin." (PMID 31119098, 2019). "As for MMP10 until now there are no studies assessing MMP12 expression in colon cancer patients ́ sera in regard with overall survival." (PMID 27431388, 2016). "However, MMP9, MMP12 and TIMP3 proteins were increased in colon cancer cells." (PMID 32171282, 2020). "However, to our knowledge until now there is no study assessing serum MMP10 and MMP12 level in a homogenous collective of colon cancer patients’ sera in regard to overall survival." (PMID 27431388, 2016).
lung disease (15 papers, 2010 to 2025). "A pathogenic role for matrix metalloproteinase 12 (MMP12) in lung disease is supported by multiple lines of evidence." (PMID 39437760, 2024). "In addition, SNP in the MMP-12 promoter (rs2276109) and a tightly linked SNP (rs737693) were seemed to be positively associated with severity of CF lung disease." (PMID 39011515, 2024). "Simultaneously, along with the increase of these proteins, BG decreased macrophage metalloproteinase (MMP12–2.87-fold decrease), an inflammatory enzyme responsible for the host tissue damage belonging to the family of proteins implicated in the pathogenesis of CF lung disease." (PMID 38850343, 2024). "In the current study, the O3 exposure of Scnn1b-Tg+ lung disease resulted in alveolar space enlargement, which is likely an outcome of enhanced macrophage and neutrophil recruitment, and an increase in MMP12-expressing macrophages." (PMID 40496925, 2025). "MMP-12 activity was found to be elevated on the surface of airway macrophages in bronchoalveolar lavage from young CF children with early lung disease." (PMID 39011515, 2024). "Taken together, our data at the gene and protein levels strongly suggest that MMP12 is central to the development of otherwise unrelated adult lung diseases in mice exposed in utero to SHS." (PMID 34912233, 2021). "Our findings, however, revealed that Mmp12 is upregulated at both the gene and protein levels in these three separate adult lung disease models following in utero SHS exposures." (PMID 34912233, 2021). "This gene up-regulation was supported at the protein level with significantly increased expression of MMP12 protein in these three lung disease models." (PMID 34912233, 2021). "Collectively, these studies identified MMP12 secreted by activated macrophages as an additional protease contributing to the in vivo pathogenesis of structural lung damage in CF-like lung disease." (PMID 27456476, 2016). "Further, whole-genome expression profiling as an unbiased bottom-up approach led to the identification of MMP12 released from activated macrophages as an important contributor to tissue damage in CF-like lung disease." (PMID 27456476, 2016). "Similar to the results obtained in βENaC-Tg mice, these studies detected increased activity of MMP12 at the macrophage surface even in children with CF with early lung disease." (PMID 27456476, 2016). "These assays can be used to evaluate MMP-12 as a biomarker for lung disease, and to monitor efficacy of potential therapeutic compounds." (PMID 20678199, 2010). "Evidence citing the involvement of MMP-12 in lung disease is provided both by genetics and by functional inhibition of MMP-12 in animal models." (PMID 20678199, 2010). "In all lung disease models, Mmp12 upregulation was supported at the protein level." (PMID 34912233, 2021). "We also checked two other lung-disease-related proteases, MMP12 and ADAM10." (PMID 31562139, 2019). "In comparison, current knowledge on the role of MMP12 in CF lung disease remains limited." (PMID 27456476, 2016). "It is possible that when irreversible pulmonary disease is established, increased MMP-12 is a consequence of disease severity and not its cause." (PMID 24146820, 2013). "Therefore our data confirm that the recruitment of proinflammatory recently migrated monocytes from the blood are responsible for the increase in MMP-12 and has an important role in the pathogenesis of lung disease induced by acute lung inflammation." (PMID 24058452, 2013). "MMP-12 (macrophage elastase) is a protease known to be involved in the progression of lung disease." (PMID 20678199, 2010). "Our data show that MMP12 is up-regulated at the gene and protein levels in three distinct adult lung disease models following in utero SHS exposures, suggesting that MMP12 is central to in utero SHS-aggravated lung responses." (PMID 34912233, 2021). "The role of MMP12, SPP1, AHRR and CYP1B1 in cigarette smoke-related lung diseases have been well described and studied." (PMID 24663285, 2014).
fibrosis (14 papers, 2006 to 2025). the formation of excess fibrous connective tissue in an organ or tissue in a reparative or reactive process. "Loss of MMP-12 production resulted in a modest reduction in granuloma-associated fibrosis at the peak of the response, but similar pathology was also observed at later time points, indicating that MMP-12 plays a modest role in generating fibrosis." (PMID 24713275, 2014). "Though MMP12 expression was found to be significantly increased in the cirrhotic patients and F4 cirrhosis stage compared with F1-3 stages of fibrosis, serum MMP12 showed a rather weak correlation with TE score (r = 0.3302)." (PMID 31903104, 2020). "Mmp12 plays an important role in lung tissue remodeling and serves as marker for related acute and chronic lung diseases like fibrosis and COPD." (PMID 29463257, 2018). "Considering the relation of Mmp12 to chronic pulmonary effects like fibrosis, potential adverse reactions due to long-term BaSO4 become more likely." (PMID 29463257, 2018). "Hence, we investigated the effect of MMP-12 deficiency in bleomycin-induced fibrosis model which hitherto has not been related." (PMID 16504062, 2006). "In LX2 fibrosis cells, expression of genes involved in ECM accumulation (TIMP1) and degradation (MMP9, MMP12, MMP13) were notably altered via JT003 exposure." (PMID 33199780, 2020). "The expression levels of MMP12 in the choroid of normal mice and the non-lesion sites of fibrosis eyes were comparable." (PMID 35382832, 2022). "Confocal microscopy detected discrete MMP12 expression in the choroid and occasionally the sclera of normal mouse eyes as well as in the non-lesion area of the choroid from fibrosis eyes." (PMID 35382832, 2022).
glioma (13 papers, 2009 to 2025). A benign or malignant brain and spinal cord tumor that arises from glial cells (astrocytes, oligodendrocytes, ependymal cells). "used a three-dimensional matrix and revealed that some proteinases are associated with TNC-mediated invasiveness, such as MMP-12 in U178 and U251 glioma cell lines, as well as ADAM-9 in glioma patient-derived GSC lines." (PMID 36033448, 2022). "An elevated miR-107 expression suppressed growth, migration and invasion abilities of glioma cells, directly targeting Notch2 and inhibiting Notch2, Tenascin-C, MMP-12 and Cox-2 expression." (PMID 30583549, 2018). "Sixty glioma-associated targets were associated with CHR, such as MDR transporters (ABCB1, ABCC1, ABCG2), cyclin-dependent kinases (CDK1, CDK6), matrix metalloproteinases (MMP2, MMP9, MMP12), and genes related to inflammation or oxidative stress (NOS2, NOX4)." (PMID 40963691, 2025). "Tenascin-C is a favorable substrate for glioma invasiveness; its effect is mediated through MMP-12." (PMID 36980765, 2023). "In addition, the reduced mRNA and protein expressions of MMP-12 in C6 rat glioma cells transfected with plasmids expressing MMP-12 shRNA have validated the in vitro efficiency of the designed, constructed, and synthesized MMP-12 shRNA expressing plasmids." (PMID 25955565, 2015). "More importantly, enhanced expression of MMP12 is correlated with local recurrence and metastatic disease in NSCLC patients and with glioma and endometrial adenocarcinoma cell invasion." (PMID 35313071, 2022). "MMP-12 has previously been associated with blood-brain barrier disruption via tight junction protein degradation after focal cerebral ischemia, while MMP-19 was associated with gliomas, but no studies had associated them with PNN formation or degradation." (PMID 37496706, 2023).
lung adenocarcinoma (13 papers, 2013 to 2025). A carcinoma that arises from the lung and is characterized by the presence of malignant glandular epithelial cells. "The early-stage lung adenocarcinoma (LUAD) prognostic model was constructed through the cancer genome atlas (TCGA) database, and three target genes (MMP12, NFE2, HOXC8) were screened to calculate the risk score of early-stage LUAD." (PMID 36650426, 2023). "For instance, MMP12 was highly expressed in lung adenocarcinoma, and its knockdown distinctly inhibited the growth and invasion of lung adenocarcinoma cells." (PMID 35265129, 2022). "Elevated levels of MMP-12 were also correlated with pathological stage and metastasis of lung adenocarcinoma." (PMID 33892690, 2021). "Consistent with published data, the present gene array-based study of various TNM stages of lung adenocarcinoma further confirmed the role of MMP-12 in the metastasis of NSCLC and its value as a potential marker for predicting the prognosis of the disease." (PMID 24137407, 2013). "Given that MMP12 blockage restrained lung adenocarcinoma metastasis, targeting MMP12 could potentially provide therapeutic benefits for both renal injury and cancer progression." (PMID 40810645, 2025). "MMP12 inactivation could inhibit lung adenocarcinoma cells' growth, invasion, and metastasis." (PMID 36106139, 2022). "Hence, targeting MMP-12 for the treatment of lung adenocarcinoma seemed promising." (PMID 33892690, 2021). "In patients with lung adenocarcinoma (LAC), the expression of MMP-12 is significantly increased in cancer tissues, and MMP-12 expression is closely related to the pathological stage and lymph node metastasis of LAC patients." (PMID 38511770, 2024). "Compared with the stage I samples, NAG-1, MAGE-A3, MALAT-1 and MMP-12 were significantly upregulated in stage II and IIIA lung adenocarcinoma samples." (PMID 24137407, 2013).
cervical carcinoma (12 papers, 2012 to 2025). A carcinoma arising from either the exocervical squamous epithelium or the endocervical glandular epithelium. "Elevated expression of MMP-12 was reported to be associated with cancer malignancy in non-small cell lung cancer, hepatocellular carcinoma, cutaneous melanoma, and cervical carcinoma." (PMID 34331103, 2021). "Similarly, we observed that the higher expression of MMP12 is linked to lower survival probability of patients with cervical cancer." (PMID 33958583, 2021). "Ectopic expression of MTA2 enhances the metastatic potential of cervical cancer cells via promoting AP1-mediated MMP12 expression." (PMID 38474064, 2024). "Previous studies have found that MTA2 regulates MMP12 expression and is involved in cervical cancer metastasis." (PMID 36741260, 2023). "We demonstrated the in vivo effects of MMP12-knockdown on the metastasis of cervical cancer cells by using a xenograft mouse model." (PMID 33958583, 2021). "According to these results, AP-1 plays an important role in MTA2-mediated MMP12 expression in cervical cancer cells." (PMID 33958583, 2021). "MTA2 and MMP12 were highly expressed in cervical cancer HeLa and SiHa cells but weakly expressed in CC7T/VGH and C33A cells." (PMID 33958583, 2021). "The phosphorylated YB1 then interacts with AP1 to disrupt the transcriptional activity of AP1, leading to the downregulation of MMP12 in cervical cancer cells." (PMID 33958583, 2021). "In clinically isolated cervical carcinomas, some MMPs, including MMP-12, exhibited increased levels of expression." (PMID 34331103, 2021). "MMP12 was highly expressed in cervical tumor tissues and correlated with the poor survival rate of patients with cervical cancer." (PMID 33958583, 2021). "Moreover, SCs displayed increased protein expression of FGF17, CTSS and MMP‐12 after co‐cultivation with cervical cancer cells." (PMID 37830980, 2023). "We also showed that MTA2 is highly expressed in cervical tumors, suggesting that MTA2/MMP12 could be a potential poor prognostic marker for cervical cancer." (PMID 33958583, 2021). "Collectively, these findings indicated that MTA2 plays a key role in regulating MMP12 expression in HPV-positive cervical cancer cells, suggesting that MTA2 may be involved in the HPV-induced carcinogenesis of cervical cancer." (PMID 33958583, 2021). "Moreover, ASK1 silencing not only restored the metastatic potential of MTA2-knockdown cervical cancer cells and MMP12 expression but also diminished the activation of MEK3 and p38 in response to MTA2 knockdown." (PMID 33958583, 2021). "We then explored the role of MMP12 in the carcinogenesis of cervical cancer." (PMID 33958583, 2021). "In addition, MMP12 is overexpressed in HPV-positive cervical cancer cell lines, suggesting that it is involved in the pathogenesis of cervical cancer." (PMID 33958583, 2021). "Collectively, targeting both MTA2 and MMP12 may be a promising strategy for the treatment of cervical cancer." (PMID 33958583, 2021). "Thus, we hypothesized that MTA2 may regulate MMP12 expression and is involved in cervical cancer metastasis." (PMID 33958583, 2021). "Thus, we first investigated whether MTA2 regulates MMP12 in human cervical cancer cell lines." (PMID 33958583, 2021). "In the present study, we further demonstrated that silencing MTA2 clearly inhibits the metastasis of cervical cancer cells by inducing the ASK1/MEK3/p38/YB-1 axis and the consequent suppression of MMP12." (PMID 33958583, 2021). "Results showed that MTA2 and MMP12 were highly expressed in cervical cancer cells, and MTA2 knockdown reduced MMP12 expression and inhibited the metastasis of cervical cancer cells in xenograft mice." (PMID 33958583, 2021). "Here, we confirmed that cervical cancer cells upregulated the expression of MMP2, MMP9, and MMP12 of SCs." (PMID 32064233, 2020). "In turn, SCs activation leads to PNI of cervical cancer by secreting FGF17, CTSS and MMP‐12." (PMID 37830980, 2023).